NAT2 (N-acetyltransferase 2)
Diseases named in the same sentence as NAT2 in open-access papers (continued):
Sharing a sentence is not in itself a finding about the gene and the disease.
bladder cancer (continued). "Genetic polymorphisms in detoxification enzymes such as NAT2 and CYP1A2 were shown to modify bladder cancer and NHL risk in susceptible individuals." (PMID 41399670, 2026). "These loci included 14 previously reported bladder cancer-associated genes (eg, GSTM1 and NAT2) and 3 novel loci near MSX2, RAPGEF5, and MIPOL1 genes." (PMID 39898788, 2025). "This was justified by the fact that NAT2 detoxifies aromatic amines (primary bladder cancer carcinogen in tobacco), and hence the effect of smoking becomes limited to smokers." (PMID 37686494, 2023). "The NAT2 enzyme plays an important role in detoxifying aromatic amine carcinogens, which are known bladder cancer-related carcinogens in cigarette smoke." (PMID 36310059, 2023). "Examples are case-only studies of the interaction between the N-acetyltransferase 2 (NAT-2) genetic polymorphisms and cigarette smoking on bladder cancer risk." (PMID 37152190, 2022). "There is a relationship between NAT2 acetylation status with some diseases like bladder cancer, colorectal cancer, rheumatoid arthritis, and diabetes." (PMID 32626768, 2020). "A tag SNP for NAT2 acetylator status (rs1495741) was identified in a bladder cancer GWAS in Europeans." (PMID 29036176, 2017). "Future studies are warranted to investigate the interaction between NAT2 and exposure to HCA carcinogens on risk of bladder cancer." (PMID 27223070, 2016). "Genetic variants in the aromatic amines detoxification enzymes have been identified to be associated with bladder cancer risk, including the GSTM1 deletion (null genotype) and the NAT2 slow acetylator genotypes." (PMID 23752272, 2013). "Mutations in DNA repair genes (XRCC3) and variants in genes coding for xenobiotic-transforming enzymes (NAT2, GSTM1, GSTP1 and NQO1) have been shown to modify the susceptibility to bladder cancer." (PMID 19755987, 2009). "He presented the results of a previously published study on the association between N-acetyl transferases 2 (NAT2) and gluthatione S-transferases-M1 (GSTM1) polymorphisms with bladder cancer risk." (PMID 22275976, 2008). "Exclusive PHD use was strongly associated with increased bladder cancer risk among individuals with the NAT2 slow acetylation genotype and those lacking the NAT1∗10 genotype." (PMID 41399670, 2026). "Moreover, genes such as NAT2, TP63, GSTM1, MYC, TACC3‐FGFR3, PSCA, CLPTM1L‐TERT, APOBEC3A‐CBX6, UGT1A, and CCNE1 get mutated in bladder cancer." (PMID 40755497, 2025). "It has also been estimated that a slow acetylation phenotype in both GSTM1 and NAT2 may account for up to 31% of bladder cancer case patients." (PMID 39898788, 2025). "NAT2 catalyzes both N-acetylation and O-acetylation reactions; modifying carcinogenesis risk with respect to NAT2 genotype, as demonstrated for carcinogens like 4-aminobiphenyl (ABP) in breast and urinary bladder cancer risk." (PMID 32372066, 2020). "Multiple previous studies have consistently shown the interaction between the NAT2 gene and smoking on bladder cancer, where such interaction is evident because the observed odds ratio is 2.89 while the odds ratio in the presence of both factors is predicted to be 1.69 by the multiplicative model." (PMID 30792419, 2019). "We re-analyzed this bladder cancer dataset to confirm the NAT2-smoking interaction." (PMID 30792419, 2019). "The nuclear matrix protein 22 (NMP22), bladder cancer-4 (BLCA-4), and total level proteins NMP22 and BLCA-4 (NMBL) in BC patients with genetic predisposition NAT2 (classified as slow acetylators, SA), DNA damage (8-OHdG), and detoxification by isoenzyme GSTπ activity were measured." (PMID 28929116, 2017). "NAT2 acetylation status was determined by both single nucleotide polymorphisms (SNPs) and caffeine metabolic ratio (CMR), in a population-based study of 494 bladder cancer patients and 507 control subjects in Shanghai, China." (PMID 27223070, 2016).
bladder cancer (continued). "None have studied NAT2 acetylation status simultaneously inferred by genotype and phenotype in relation to risk of bladder cancer." (PMID 27223070, 2016). "In addition, two previously reported bladder cancer risk loci 1p13.3 (glutathiones transferase, GSTM1, deletion) and 8p22 (N-acetyltransferase 2, NAT2, intergenic region) were further validated in the GWAS studies." (PMID 27738493, 2016). "Genotype of the NAT2 gene would not be altered by the disease status, thus the observed association between the SNP-inferred acetylation status and bladder cancer risk are unlikely to be confounded by the retrospective study design." (PMID 27223070, 2016). "Common polymorphisms in two carcinogen detoxification genes, N-acetyltransferase 2 (NAT2) and glutathione-S-transferase M1 (GSTM1), have been consistently associated with bladder cancer risk and several studies suggested that the NAT2 slow acetylation genotype interacts with smoking intensity." (PMID 27809812, 2016). "Additionally, genetic studies have demonstrated that functional polymorphisms in two genes involved in carcinogen metabolism (N-acetyltransferase 2 [NAT2] and glutathione S-transferase M1 [GSTM1]) are associated with bladder cancer risk." (PMID 22238607, 2012). "By contrast, a previous study from Spain, the Spanish Bladder Cancer Study, failed to confirm an increased risk of bladder cancer in a population of personal hair dye users and found no increased risk in NAT2 slow acetylators." (PMID 22581032, 2012). "Our findings are biological plausible and are consistent with a recent study in Spain, which found that NAT2 slow acetylators have an increased risk of bladder cancer that was stronger for cigarette smokers compared to never smokers." (PMID 17026750, 2006). "Furthermore, we did not observe any statistically significant effect modification by cigarette smoking status for the NAT2 or NAT1 genotypes and bladder cancer risk (p for interaction > 0.4)." (PMID 17026750, 2006). "After stratification by cigarette smoking status, the association between NAT2 slow acetylation genotype and bladder cancer risk was stronger but not statistically significant among ever smokers (OR = 1.76; 95% CI, 0.88–3.52) (p for interaction = 0.15)." (PMID 17026750, 2006). "We compared the distributions of the GSTM1, GSTT1, NAT1, and NAT2 genotypes between incident and prevalent bladder cancer cases in men and women separately to determine whether the variant alleles were associated with survival." (PMID 17026750, 2006). "Only five of the 21 studies reported results separately for the effect of NAT2 on bladder cancer risk in smokers and non-smokers." (PMID 10917561, 2000). "For example, a case–control study conducted in the US showed that the association between cruciferous vegetable intake and bladder cancer risk might be modified by the GSTM1 genotype, and the protective effect of cruciferous vegetables was observed only in subjects carrying the NAT2-slow genotype." (PMID 37828430, 2023). "NAT1 and NAT2 are two members of the N-acetyltransferases (NAT) family that encode polymorphic enzymes catalyzing the metabolic activation of heterocyclic aromatic amines (HCAs), which have been considered established carcinogens in human colorectal cancer and urinary bladder cancer." (PMID 34322151, 2021). "A positive association between meat intake and risk of bladder cancer has also been demonstrated among never smokers with genotype-inferred NAT2 rapid acetylation status, suggesting a possible activation effect of NAT2 on HCA through O-acetylation pathway in the urinary bladder." (PMID 27223070, 2016). "An example is the SNP rs149574 in N-acetyltransferase 2 (NAT2) gene, which is functional and has been reported to modify the effect of smoking in bladder cancer." (PMID 30373182, 2018).
breast cancer (24 papers, 2005 to 2024). A primary or metastatic malignant neoplasm involving the breast. "Some polymorphism of arylamine N-acetyltransferases types 1 and 2 (NAT1, NAT2) confer a higher risk of developing breast cancer." (PMID 32085420, 2020). "Studies have reached differing conclusions about the role of possible polymorphisms of the NAT2 gene on breast cancer susceptibility." (PMID 28865460, 2017). "The results reported in the current study suggest that the human NAT1 (an ortholog of rat NAT2) phenotype and prepubescent carcinogen exposure should be studied as additional factors in human breast cancer susceptibility." (PMID 28359264, 2017). "We conducted in vivo studies using F344.WKY-Nat2rapid/slow rats, congenic at rat Nat2 for high (rapid) and low (slow) arylamine N-acetyltransferase activity, to assess a possible role for rat NAT2 in mammary tumor susceptibility." (PMID 28359264, 2017). "The evidence for a causal relationship between processed meat and breast cancer is limited and mainly observed in case-control studies where a genetic polymorphism in N-acetyltransferase 2 has been investigated in relation to the presence of HCA in foods." (PMID 26393643, 2015). "A previous study revealed that the relationship between smoking and risk of breast cancer was modified by the NAT1 or NAT2 genotype among postmenopausal women." (PMID 24204725, 2013). "Another recent meta-analysis further suggested that NAT2 polymorphisms contribute to the risk of breast cancer when smoking history is taken into account." (PMID 24204725, 2013). "Our results from logistic regression analysis regarding the association of NAT2 with breast cancer risk, as previously reported, are in line with findings from other studies." (PMID 21080951, 2010). "A further interesting finding is that mEH and NAT2 gene polymorphisms represent a prognostic variable for predicting survival and relapse after treatment in breast carcinoma patients." (PMID 18423013, 2008). "In this study, mEH gene polymorphism was also associated with the early onset of breast carcinoma whereas polymorphisms in NAT2 and CYP2D6 genes are also correlated with late onset of breast carcinoma." (PMID 18423013, 2008). "A combined genotype analysis revealed that mEH (C/C)-NAT2 slow acetylator genotype combinations was associated with breast carcinoma risk (OR = 2.18; p = 0.04)." (PMID 18423013, 2008). "The mEH (C/C) mutant and the NAT2 slow acetylator genotypes were significantly associated with breast carcinoma risk (p = 0.02; p = 0.01, respectively)." (PMID 18423013, 2008). "Conversely, the mEH (C/T)-NAT2 (Rapid/Slow acetylators) combination was highly associated with a protective effect against breast carcinoma (OR = 0.44; p = 0.0004)." (PMID 18423013, 2008). "Among the 17 genotypes, the heterozygous slow acetylators NAT2*5A/*6B were found to be statistically significant as a risk factor for breast carcinoma." (PMID 18423013, 2008). "This study investigated the susceptibility and prognostic implications of the CYP2E1, CYP2C19, CYP2D6, mEH and NAT2 gene polymorphisms in breast carcinoma patients." (PMID 18423013, 2008). "The present study first investigated the relationship between DNA variants in Cytochrome P 450 (CYP) -2E1, -2C19, -2D6, microsomal Epoxide Hydrolase (mEH) and N-acetyltransferase -2 (NAT2) enzymes and susceptibility to breast carcinoma." (PMID 18423013, 2008). "The SULT1A1*1/*1 genotype in combination with NAT2 fast acetylator status, however, appeared to increase breast cancer risk in women exposed to tobacco smoke." (PMID 15743503, 2005). "We conducted the present study to elucidate the potential role of SULT1A1 genotype alone and in combination with NAT2 genotype as a modifier of susceptibility to breast cancer associated with exposure to tobacco smoke among predominantly premenopausal women." (PMID 15743503, 2005).
breast cancer (continued). "This investigation is the largest case-only study to examine the interaction between NAT2 acetylation status and history of tobacco exposure as it relates to the risk of breast cancer." (PMID 15987434, 2005). "Postmenopausal women who smoke and have a reduced ability to detoxify by-products of tobacco smoke, as measured by their NAT2 genotype (slow acetylators), have an excess risk of breast cancer." (PMID 15987434, 2005). "Our data do not suggest a strong influence of SULT1A1 genotype alone or in combination with NAT2 on the risk for breast cancer." (PMID 15743503, 2005). "We observed a somewhat stronger risk in women with NAT2 slow genotype, providing some evidence that the ability to detoxify tobacco carcinogens may modify the risk of tobacco exposure for breast cancer." (PMID 36967121, 2023). "In conclusion, this study suggests that CYP2D6, mEH and NAT2 gene polymorphisms may be attractive susceptibility markers for breast carcinoma." (PMID 18423013, 2008). "Heterozygous NAT2*12A/*5B genotype (intermediate acetylator) was significantly more frequent in controls than in patients (8.86% vs 2.41%) indicating a protective effect of this gene variant against breast carcinoma (OR = 0.25, p = 0.001)." (PMID 18423013, 2008). "In addition, studies which attempted to investigate the NAT2 genetic polymorphisms as an independent risk marker for breast carcinoma have failed." (PMID 18423013, 2008). "To date, numerous polymorphisms on the NAT2 gene have been identified, which has furthered our understanding of NAT2 phenotypes and improved our ability to assign acetylation status to the breast cancer cases in this study." (PMID 15987434, 2005). "In addition, the study involved the largest number of breast cancer cases used to investigate the interaction between NAT2 acetylation status and exposure to tobacco smoke as related to breast cancer risk." (PMID 15987434, 2005). "Thus, NAT2 slow acetylator genotype was significantly associated with breast carcinoma risk." (PMID 18423013, 2008). "Another study proposed that microRNA-6477-5p increased anoikis sensitivity by targeting NAT1 (an important paralog of NAT2) in breast cancer." (PMID 34867333, 2021). "Our online search identified 4 SNPs — rs1800562 in HFE, rs174577 in FADS2, rs651007 in ABO and rs4921915 in NAT2 — related to LDL-C, TCHO, and/or TG levels, which have been reported to influence breast cancer risk." (PMID 34229617, 2021). "A novel role for rat NAT2 in mammary cancer was discovered unrelated to carcinogen metabolism, suggesting a role for human NAT1 in breast cancer." (PMID 28359264, 2017). "The results of this study provide new evidence and insight into a role of rat NAT2 and, by analogy, human NAT1 in breast cancer susceptibility." (PMID 28359264, 2017). "Rapid acetylator congenic rats had a significantly (p<0.05) shorter latency for development of their first palpable mammary tumor compared to slow acetylator NAT2 congenic rats after administration of MNU in females treated at either 3 or 8 weeks of age." (PMID 28359264, 2017). "There are also reports of significant interactions with smoking and polymorphisms in carcinogen metabolism genes NAT2 and CYP1A1 as well as breast cancer susceptibility single-nucleotide polymorphisms." (PMID 29162146, 2017). "Both regression and Bayes Model Averaging highlighted a significant effect of NAT1*10 on breast cancer, while regression analysis also suggested a significant effect for packyears and for the interaction of packyears and NAT2." (PMID 21080951, 2010). "The development of mouse models of breast cancer is important, and it is essential to explore the biological role of mouse Nat2." (PMID 18280460, 2008).
breast cancer (continued). "CYP2E1, CYP2C19, CYP2D6, mEH and NAT2 genotype frequencies in control subjects and in patients with breast carcinoma." (PMID 18423013, 2008). "Multivariate logistic regression analysis was used to estimate breast cancer risk associated with the SULT1A1 Arg213His polymorphism alone and in combination with NAT2 genotype in relation to smoking." (PMID 15743503, 2005). "By genotyping more SNPs with a more accurate method and by implementing a case-only design, our analysis provides a more valid assessment of the multiplicative interaction between NAT2 genotype and exposure to tobacco smoke in relation to breast cancer." (PMID 15987434, 2005). "Notably, a retrospective analysis of publicly available NAT1 and NAT2 gene expression data in established breast cancer cell lines, primary breast tumor tissues, and normal breast tissues showed a small positive correlation between the two genes." (PMID 35046826, 2021). "According to Egeberg and collaborators, with respect to slow acetylators, the incidence ratio of breast cancer among those carrying the fast NAT1 genotype was 1.43 (95% CI 1.03–1.99) and among those with the intermediate/fast NAT2 allele, risk was 1.13 (95% CI 0.83–1.54)." (PMID 32085420, 2020). "There is an extensive literature examining whether or not genetic profiles that alter the efficacy or speed of N-acetyltransferase activation, especially through the N-acetyltransferase 2 (NAT2)-regulated pathway, might alter susceptibility to breast cancer." (PMID 28865460, 2017). "Our results in Nat2 congenic rats suggest that human genetic variation resulting in differential NAT1 activity may influence human breast cancer." (PMID 28359264, 2017). "However, recent evidence does not suggest that polymorphisms in genes that metabolize HCAs (N-acetyltransferase 2 and CYP 1A12) modify colon or breast cancer risk." (PMID 26393643, 2015). "In a meta- and pooled analysis including 13 studies, NAT2 was not independently associated with breast cancer risk but smoking was found to be associated with increased risk in NAT2 slow acetylators but not in rapid acetylators." (PMID 21080951, 2010). "The present population-based case-control study of breast cancer in Germany evaluated the role of genetic polymorphisms in Phase I and II enzymes NAT1 and NAT2 in the AA pathway and CYP1A1, CYP1B1, GSTM1 and GSTT1 in the PAH pathway and cigarette smoke exposure in breast carcinogenesis." (PMID 21080951, 2010). "For instance, in Taiwanese breast cancer cases it was found that breast cancer risk was not significantly influenced by NAT2 polymorphisms." (PMID 18423013, 2008). "Whether the effects on inhibition of Nat2 activity in vitro may be physiologically relevant for breast cancer prevention or therapy will require further analysis." (PMID 18280460, 2008). "In combination with NAT2 fast acetylator status, however, the SULT1A1*1/*1 genotype might increase breast cancer risk in women exposed to tobacco smoke." (PMID 15743503, 2005). "There was also no major effect of SULT1A1 genotype in combination with NAT2 acetylator status on breast cancer risk (data not shown)." (PMID 15743503, 2005). "Breast cancer risk was significantly increased in women with NAT2 slow polymorphism (RR 1.19; 95% CI, 1.09–1.30), but not in those with NAT2 fast polymorphism (RR 1.00; 95% CI, 0.86–1.17), although the two estimates were not significantly heterogeneous (eFigure 3)." (PMID 36967121, 2023). "The role of NAT1 in breast cancer, until recently, was thought to center on NAT1’s ability to metabolize/activate carcinogens, however it has been shown that rats with higher Nat2 expression (orthologous to human NAT1) had greater mammary tumor susceptibility, independent of carcinogen metabolism." (PMID 35046826, 2021).